AKT1 (AKT serine/threonine kinase 1)
Diseases named in the same sentence as AKT1 in open-access papers (continued):
Sharing a sentence is not in itself a finding about the gene and the disease.
nasopharyngeal carcinoma (83 papers, 2011 to 2026). A carcinoma arising from the nasopharyngeal epithelium. "The AKT1 AA haplotype for both rs1130233 and rs2494732 is reported to confer an elevated risk of nasopharyngeal carcinoma; the haplotype containing variant alleles of rs1130214 and rs3803300 polymorphisms significantly increases susceptibility to oral squamous cell carcinoma." (PMID 26317520, 2015). "For instance, it promotes nasopharyngeal carcinoma invasion by sponging miR-373-3p and upregulating g AKT1 expression." (PMID 41390674, 2025). "In the tumour microenvironment of human nasopharyngeal carcinoma, IL‐17A mediates AKT1 acetylation via p300, activating the Akt signalling pathway and stimulating the proliferation of nasopharyngeal carcinoma cells." (PMID 39778006, 2025). "The results of their network analysis experiments showed that the anti-nasopharyngeal carcinoma effect of CEP was related to eight core targets such as EGFR, AKT1, PIK3CA and mTOR." (PMID 41368570, 2025). "Previously, we found that Aurora-A promoted EMT and invasion in nasopharyngeal carcinoma mediated by mitogen-activated protein kinase (MAPK) phosphorylation, and increased laryngeal squamous cell carcinoma (LSCC) cell growth and migration mediated by activation of Akt1." (PMID 25082261, 2014). "Two core networks were generated by hub gene screening using the MCODE plugin of Cytoscape, and AKT1, CTNNB1, HSP90AA1, ESR1, CCND1, and EGFR were identified as key hub proteins, which may play an important role in the efficacy of icaritin in the treatment of nasopharyngeal carcinoma." (PMID 36467051, 2022). "Previously, we found that Aur-A promoted epithelial–mesenchymal transition and invasion in nasopharyngeal carcinoma (NPC) mediated by mitogen-activated protein kinase (MAPK) phosphorylation, and increased LSCC cell growth and migration mediated by activation of Akt1." (PMID 23437271, 2013).
triple-negative breast carcinoma (81 papers, 2012 to 2026). An invasive breast carcinoma which is negative for expression of estrogen receptor (ER), progesterone receptor (PR), and human epidermal growth factor receptor 2 (HER2). "It was further demonstrated that loss of function of AKT1 isoform is associated with reduced sensitivity towards cisplatin treatment in triple-negative breast cancers cellular and syngeneic mice models." (PMID 33227065, 2020). "Since, use of cisplatin is one of the main therapeutic strategies to treat the triple-negative breast cancer patients, our studies have demonstrated that loss of function of AKT1 isoform in particular has ability to affect cancer cell sensitivity against the treatment." (PMID 33227065, 2020). "The PI3K/AKT/mTOR signalling pathway is often activated in triple-negative breast cancer through activating mutation in PIK3CA and AKT1 or inactivating alterations in PTEN." (PMID 35954393, 2022). "TRIB1 knockdown in triple-negative breast cancer cells results in inhibited AKT1 phosphorylation and activity." (PMID 34205360, 2021). "Our laboratory recently showed that Akt1 expression plays a major role in the radiosensitivity of triple negative breast cancer." (PMID 34065268, 2021). "PIK3CA and AKT1 mutations were found to be particularly enriched in the luminal B/HER2− subtype, NF1, and ERBB2 mutations were enriched in the luminal B/HER2+ mutation, and PTEN mutations were enriched in triple-negative breast cancer." (PMID 33173047, 2020). "Furthermore, knockdown of Snail using siRNA caused reduced expression of ABCG2 and a diminished number of tumorospheres, thereby indicating that AKT1 is negatively regulating the stemness and cisplatin resistance in triple-negative breast cancers." (PMID 33227065, 2020). "Therefore, AKT1-inhibition in combination with radiotherapy might be an effective treatment option for triple-negative breast cancer (TNBC)-patients with brain metastases." (PMID 37483521, 2023). "Regulation of NF-κB, via AKT1 inhibition, is purported to be critical in TRIB1 regulation of the cell cycle and TRAIL drug response in triple-negative breast cancer cells." (PMID 34205360, 2021). "Because reduced AKT3 expression levels in triple-negative breast cancers are reported to increase sensitivity to GSK690693, FPKM values of AKT1/2/3 were checked in GUMC220/221." (PMID 29419396, 2018). "Capivasertib and ipatasertib (both AKT inhibitors) have both demonstrated clinical activity in combination with paclitaxel in triple-negative-breast cancer (TNBC) in Phase II clinical studies, with more pronounced benefit in patients with PIK3CA/AKT1/PTEN mutant tumours." (PMID 36241868, 2022). "On the basis of our data, the treatment of triple negative breast cancer in a non-metastatic stage with an AKT1/2 inhibitor in combination with other established drugs or mTOR inhibitors like RAD001 should be taken forward in further studies." (PMID 33670586, 2021). "Similarly, triple-negative breast cancer cell lines, BT-549 and MDA-MB-231, with high proliferative and invasive properties, displayed higher expression levels of AKT1/2." (PMID 33227065, 2020). "This pathway is frequently activated in triple negative breast cancer (TNBC), via molecular abnormalities such as PIK3CA mutations or loss of PTEN function.As has been observed previously, PIK3CA oncogene mutations were more common in TNBC unlike Akt1 and PTEN mutations." (PMID 30227836, 2018).
acute myeloid leukemia (67 papers, 2010 to 2026). Acute myeloid leukemia (AML) is a group of neoplasms arising from precursor cells committed to the myeloid cell-line differentiation. "Nanoproteomic assays have already been developed and tested for several cancers, and in the context of metabolism, assays for AKT1/2/3 and 4EBP1 are able to quantify signaling in acute myeloid leukemia cells." (PMID 28362357, 2017). "Our present work identified ID1, inhibitor of DNA binding 1, HLH protein, was significantly down-regulated in both MDA-MB-231BR AKT1_KO cell lines and in line with this, the regulation of AKT-signaling by affecting ID1 was reported earlier in acute myeloid leukemia." (PMID 37483521, 2023). "Among the three AKT isoforms, AKT1 is expressed ubiquitously and a high rate of AKT1 amplification occurs in a wide range of human cancers including acute myeloid leukemia (AML), a rare but often fatal blood cancer." (PMID 36365115, 2022). "Finally, we have recently reported the identification of novel competitive AKT1 inhibitors as possible agents against acute myeloid leukemia (AML)." (PMID 37513905, 2023). "Also, Akt1/2/3 has been reported to be over activated in acute myeloid leukemia (AML)." (PMID 35669422, 2022). "The levels of PTEN or of the active Akt1-mutant E17K did also not correlate with higher Akt-T308 phosphorylation in cells from patients suffering from acute myeloid leukemia." (PMID 29562639, 2018). "Furthermore, in the carcinogenesis of acute myeloid leukemia (AML), a novel functional link has been revealed between AEG-1/MTDH and Aurora A kinase (AURKA) with regard to Akt1 activation." (PMID 25009642, 2014).
Cerebral ischemia (64 papers, 2014 to 2026). Restriction of arterial blood supply to the brain associated with insufficient oxygenation to support the metabolic requirements of the tissue. "We previously showed that this phosphomimetic mutation rescues impaired blood flow in Akt1 deficient mice subjected to wound healing assays, and improves vessel reactivity and decreases stroke size when challenged with cerebral ischemia." (PMID 24465805, 2014). "RELA, AKT1, JUN, PRKACA, PTGS2, RAF1 and CHUK were identified as four key targets associated with ischemic encephalopathy." (PMID 38285889, 2024). "Studies have shown that Akt1 overexpression reduces the infarct size after cerebral ischemia by 35% in MCAO model rats." (PMID 32218735, 2020). "Previous research confirmed that overexpressing HSP72 facilitated a satisfactory prognosis of cerebral ischemia–reperfusion injury, which may be attributed to c-Jun N-terminal kinase 3 signaling pathway inhibition and Akt1 activation." (PMID 38264043, 2023). "Once activated, AKT1 triggers a series of signal cascade reactions, which can reduce the death of brain cells, promote the growth of neural cells and vascular endothelial cells, enhance the regeneration and repair of nerve tissue and vessels, and improve neural function after cerebral ischemia." (PMID 41471340, 2025). "Activated AKT1 triggers a series of signal cascade reactions, which can reduce the death of brain cells, promote the growth of neural cells and vascular endothelial cells, enhance the regeneration and repair of nerve tissue and vessels, and improve neural function after cerebral ischemia." (PMID 37426810, 2023).
Cognitive impairment (61 papers, 2012 to 2025). Abnormal cognition is characterized by deficits in thinking, reasoning, or remembering. "Subsequent testing revealed that the patient is genetically predisposed as high risk for both psychosis (AKT1 C/C genotype) and cognitive impairment (COMT Val/Val genotype)." (PMID 33526106, 2020). "Conversely, analysis of the AKT1 and COMT genotypes revealed that over half (> 55%) of the participants had gene variants that significantly increased their risk of potentially developing psychotic symptoms and/or cognitive impairment." (PMID 33526106, 2020). "Recent studies have shown that enhancing AKT1 inhibits JNK3/caspase-3 activation and plays a neuroprotective role in ischaemia/reperfusion-induced cognitive impairment." (PMID 35656471, 2022). "Through increasing the phosphorylation of AKT (AKT serine/threonine kinase 1) and GSK-3β, AM404 at low dose ameliorated cognitive deficit and reduced Aβ, Tau hyperphosphorylation, and inflammation in hyperglycemic 3×Tg-AD mice." (PMID 33196459, 2020).
lymphoma (61 papers, 2009 to 2026). A malignant (clonal) proliferation of B- lymphocytes or T- lymphocytes which involves the lymph nodes, bone marrow and/or extranodal sites. "The molecular docking and MMGBSA analysis of the compound DMBP against a panel of lymphoma-associated protein targets—AKT1, HSP90AA1, MTOR, MAPK1, and MDM2—revealed distinct binding affinities and interaction profiles, indicative of its potential as a multi-target therapeutic agent." (PMID 40699833, 2025). "We performed this analysis using the list of proteins with an Eμ-Myc/cRel−/− lymphoma up-regulated phosphopeptide (relative to WT Eμ-Myc cells) and manually added in either AKT1, ERK1 or JNK1 to identify any potential links." (PMID 36240067, 2022).
multiple myeloma (60 papers, 2006 to 2025). "The mTOR pathway has been suggested to be a potential therapeutic target in myeloma characterized by up-regulated AKT1." (PMID 25769101, 2015). "The first combination targeted the CDK family, AKT1 and HDAC family driver targets of the LP1 myeloma cell line, while the second combination affected the CDK family, the MEK1/2 complex and NOTCH via gamma secretase." (PMID 31523388, 2019).
oral cancer (59 papers, 2012 to 2025). "Oral cancer is characterized by several hallmark features amongst which up-regulation of Akt1 and Akt2 is considered significant." (PMID 38234400, 2023). "In our analysis, we found that the silencing of Akt1 and 2 isoforms caused an increase in the percentage of cell death in oral cancer cells." (PMID 31252679, 2019). "In these HNSCC model cell lines, AKT1 inhibition induced a drastic change in the cellular morphology of the CAL33 oral cancer cell line that is associated with increased migratory and invasive capacities." (PMID 29506489, 2018). "Further, treatment of oral cancer cells with tobacco and its components such as benzo(a)pyrene and nicotine caused increased mRNA levels of Akt1 and 2 isoforms and also enhanced the aggressiveness of oral cancer cells in terms of proliferation, and clonogenic and migration potential." (PMID 31252679, 2019). "Moreover, the dataset of “The Cancer Genome Atlas” for head and neck cancer has suggested the genetic alterations of Akt1 and 2 tend to be associated with the utmost poor clinical outcome in oral cancer." (PMID 31252679, 2019). "In oral cancer, the silence of AKT1 and AKT2 inhibited the expression of COX-2, cyclinD1, and Bcl-2, which in turn inhibited cell survival." (PMID 36734243, 2023). "Specific targeting of the Akt1 and 2 isoforms would result in a better prognosis for oral cancer patients." (PMID 31252679, 2019). "Based on our investigations, it can be suggested that the selective inhibition of Akt1 or Akt2 isoforms would be a better approach for the management of oral cancer." (PMID 31252679, 2019). "In order to understand the role of Akt1 and 2 in oral cancer, the specific genes were silenced using specific siRNAs." (PMID 31252679, 2019). "Analysis of the differential expression of Akt isoforms in oral cancer tissues showed overexpression of Akt1 and 2 isoforms." (PMID 31252679, 2019). "We further found that treatment with tobacco and its components such as BAP and nicotine increased the clonogenic potential of oral cancer cells, which was reduced by silencing Akt1 and 2 isoforms." (PMID 31252679, 2019). "Akt1/2 silencing also reduced tobacco-induced aggressiveness by decreasing the clonogenic and migration potential of oral cancer cells." (PMID 31252679, 2019). "Collectively, our data indicate that Akt1 and 2 are the major players in oral cancer and can be used as a target to discover novel therapies for this disease." (PMID 29460395, 2018). "The major goal of this pilot study was to see if SBVS could be used to find novel inhibitors with action against Akt1 and Akt2 in oral cancer." (PMID 35251696, 2022). "Moreover, the elimination of AKT1/2 decreased the growth of oral cancer cells compared with the mock control." (PMID 34299129, 2021). "In addition, future studies should also be concentrated on selective inhibition of Akt1 and 2 isoforms, with experimental validation for the development of effective therapy against oral cancer." (PMID 31252679, 2019). "Moreover, the expression of Akt1 and 2 isoforms were found to be higher at the advanced stage of oral cancer." (PMID 31252679, 2019). "Our preliminary study indicated that Akt1 and 2 are primarily overexpressed in oral cancer tissues and also the TCGA dataset revealed the genetic alteration associated with Akt1 and 2 isoforms increased the transcript level but not the Akt3 isoform." (PMID 31252679, 2019). "Additionally, the expression of Akt1 and 2 isoforms varied with the different stages of cancer and it gradually increased with advanced stages of oral cancer." (PMID 31252679, 2019). "Thus, the important role of Akt1 and 2 isoforms have been elucidated in oral cancer with in-depth mechanistic analysis." (PMID 31252679, 2019). "Thus, this study demonstrates that the identified lead compounds may act against Akt1 and Akt2 in oral cancer." (PMID 35251696, 2022).
oral cancer (continued). "Therefore, it becomes evident that both Akt1 and 2 might play a significant role in clinical outcomes of oral cancer patients." (PMID 31252679, 2019). "Later, in order to establish the role of Akt1 and 2 isoforms in the pathogenesis of oral cancer, we silenced these genes using siRNA and examined its effect on the growth, survival, proliferation, and migration of oral cancer cells and the involved molecular mediators." (PMID 31252679, 2019). "This study demonstrated that Quercus infectoria possesses promising anticancer potential against oral cancer, with Nyctanthic acid emerging as a key bioactive compound targeting the PI3K‐Akt pathway through stable interaction with AKT1 (−125.426 kcal/mol)." (PMID 40933552, 2025). "High-level expression of RAC-alpha serine/threonine-protein kinase (Akt1) and RAC-beta serine/threonine-protein kinase (Akt2) is responsible for oral cancer." (PMID 35251696, 2022). "In our study, we found that treatment of oral cancer cells with tobacco and its components such as BAP and nicotine increased the transcript level of Akt1 and 2 isoforms." (PMID 31252679, 2019). "The wound healing assay was performed to analyze the effect of silencing of the Akt1 and 2 isoforms on TE, BAP, and nicotine-induced migration of oral cancer cells." (PMID 31252679, 2019). "By targeting both AKT1 and GAPDH, Nyctanthic acid may offer a more comprehensive therapeutic approach, potentially improving outcomes in oral cancer where resistance and recurrence remain major clinical challenges." (PMID 40933552, 2025). "The immunohistochemical analysis of oral cancer tissues showed an overexpression of Akt1 and 2 isoforms but not Akt3." (PMID 31252679, 2019). "In pursuit of candidate/lead molecules for oral cancer, it is hypothesized that chemical entities inhibiting the overexpression of Akt1 and Akt2 without suppressing the expression of MAOB may demonstrate promising therapeutic potential." (PMID 38234400, 2023). "It even reduced the phosphorylation of ERK1/2 and AKT1 with concomitant downregulation of cyclin D1 (CCND1), cadherin 2 (CDH2), and vimentin (VIM) and upregulation of cadherin 1 (CDH1) expression suggesting its anti-proliferative and anti-EMT effects in oral cancer." (PMID 36761830, 2022). "On exploring the TCGA dataset, it was observed that all three Akt kinase isoforms have a considerable percentage of genetic alterations in HNSCC, but in our study, the IHC analysis of oral cancer tissues showed high expression of Akt1 and 2 isoforms but not Akt3 compared to the normal tissues." (PMID 31252679, 2019).
renal cell carcinoma (58 papers, 2013 to 2026). "The AKT1 expression in human renal cell carcinoma tissue was detected by immunohistochemical staining." (PMID 35996134, 2022). "Similar to the results seen in this study, specific inhibition of Akt1 induced a significant increase in apoptotic death of renal cell carcinoma cells both in vitro and in vivo." (PMID 27533079, 2016). "Increased Akt1 and ERK1/2 activation has been linked to the malignancy of renal cell carcinoma." (PMID 38288105, 2023). "In present study, we evaluated the function of AKT and AKT1 in renal cell carcinoma." (PMID 35996134, 2022). "In present study, AKT of RCC cells was knocked down, and a set of cellular function assays were performed, considering the role of AKT1 on tumorigenesis, The expression of AKT1 in renal cell carcinoma tissue was detected by immunohistochemical staining." (PMID 35996134, 2022).